FRMD6 (FERM domain containing 6)
Synonyms: C14orf31; MGC17921; willin; EX1; c14_5320
Tractability: Antibody: UniProt places it where antibodies can reach, with high confidence; its Gene Ontology location is reachable by antibodies, with high confidence. PROTAC: ubiquitination databases record sites on it.
Gene: Protein-coding gene on chromosome 14 (51,489,100 to 51,730,727, forward strand). Ensembl gene ENSG00000139926.
Subcellular location: Cytoplasm; Cell membrane
Subcellular location (Human Protein Atlas): Mitochondria
Gene Ontology:
Molecular function: protein binding; protein sequestering activity
Biological process: positive regulation of hippo signaling
Cellular component: cytoplasm; plasma membrane; cell-cell junction; apical junction complex
Genetic constraint (gnomAD): Loss-of-function variants: 24 observed, 41.78 expected, observed/expected ratio (o/e) 0.57, 90% interval 0.41 to 0.81. The upper end of that interval is the gene's LOEUF score, 0.81, which puts it in group 3 of 6, group 1 being the genes least tolerant of losing a copy. Missense variants: 505 observed, 569.94 expected, observed/expected ratio (o/e) 0.89, 90% interval 0.82 to 0.95. Synonymous variants: 186 observed, 213.81 expected, observed/expected ratio (o/e) 0.87, 90% interval 0.77 to 0.98.
Homologues: Orthologues: chimpanzee FRMD6 (99% identical), macaque FRMD6 (99% identical), dog FRMD6 (97% identical), guinea pig FRMD6 (97% identical), pig FRMD6 (96% identical), mouse Frmd6 (94% identical), rat Frmd6 (92% identical), rabbit FRMD6 (88% identical), tropical clawed frog frmd6 (85% identical), zebrafish frmd6 (72% identical), Caenorhabditis elegans frm-1 (21% identical), Drosophila melanogaster cora (17% identical), and 5 more. Paralogues in human: EPB41L2 (22% identical), EPB41 (22% identical), EPB41L3 (21% identical), EPB41L1 (19% identical), EPB41L4B (19% identical), FRMD3 (18% identical), EPB41L4A (17% identical), FRMD5 (17% identical), EPB41L5 (16% identical), MYLIP (11% identical).
Diseases named in the same sentence as FRMD6 in open-access papers:
FRMD6 is named in the same sentence as 31 diseases in open-access papers, as found by Europe PMC text mining. Sharing a sentence is not in itself a finding about the gene and the disease. The quoted sentences say what the papers report.
breast cancer (7 papers, 2016 to 2024). A primary or metastatic malignant neoplasm involving the breast. "By contrast, activation of SAV1 and FRMD6 gene expression using the CRISPRa system led to significant inhibition of mammary tumor growth and strongly reduced tumor size." (PMID 34031411, 2021). "FRMD6 was found to serve as a tumor suppressor of human breast cancer cells and FRMD6 knockdown induces the epithelial–mesenchymal transition (EMT) in mammary epithelial cells." (PMID 27661120, 2016). "Metformin, a well-known drug for the treatment of hyperglycemia, increases Willin/FRMD6 levels in Tamoxifen and paclitaxel sensitive breast cancer cells, suggesting that Willin/FRMD6 modulation may occur in response to glucose." (PMID 34831245, 2021). "Importantly, when tested in preclinical models of TNBC orthotopic transplantation, the two individual SAV1 and FRMD6 CRISPR-KO were able to significantly facilitate primary mammary tumor growth." (PMID 34031411, 2021). "Through differential expression analysis and mutual information, we identified seven genes (NOL4, STAR, C8G, NEIL1, SLC46A3, FRMD6, and SCARF2) that are potential biomarkers in breast cancer." (PMID 39199284, 2024). "We identified seven potential genes within breast cancer: NOL4, STAR, C8G, NEIL1, SLC46A3, FRMD6, and SCARF2." (PMID 39199284, 2024). "Our analysis of drug‐sensitive breast cancer cells indicated that MET inhibited cell proliferation and invasion by increasing the expression of the classical Hippo upstream regulators, KIBRA and FRMD6." (PMID 32281270, 2020). "The expression levels of the upstream molecules in this pathway, such as Kibra, FRMD6/Willin and Merlin/NF2, were upregulated or downregulated at both the transcriptional and protein levels with overexpressing or knocking down N3ICD in MDA-MB-231 breast cancer cells, respectively." (PMID 27841855, 2016).
prostate carcinoma (7 papers, 2021 to 2024). A carcinoma that arises from epithelial cells of the prostate gland. "FRMD6 has been associated with clinical outcomes in prostate cancer." (PMID 34123815, 2021). "In conclusion, our findings identified a novel oncogenic axis, HNRNPA2B1/miR-93-5p/FRMD6, that stimulates prostate cancer progression via an m6A-dependent manner." (PMID 37215455, 2023). "After further validation through qRT-PCR and dual luciferase reporter assays, we confirmed that FRMD6 was the direct target of miR-93-5p in prostate cancer and was selected for subsequent research." (PMID 37215455, 2023). "HNRNPA2B1/miR-93-5p downregulated FERM domain-containing protein 6 (FRMD6), a cancer suppressor, and enhanced proliferation and metastasis in prostate cancer." (PMID 37215455, 2023). "Analysis of GEO datasets (GSE29079, GSE94767, and GSE3325) also showed that FRMD6 was significantly downregulated in prostate cancer tissues and metastatic tumor tissues." (PMID 37215455, 2023). "Immunohistochemistry analysis of our paired prostate tissues also verified the downregulation of FRMD6 in prostate cancer." (PMID 37215455, 2023). "In lung cancer, FRMD6 promoted the tumor growth and invasion via mTOR pathway, while FRMD6, as a tumor suppressor inhibited the carcinogenesis and progression of prostate cancer and glioma." (PMID 37280069, 2023). "Cell test and tissue test showed that FERM domain containing 6 (FRMD6) had tumor inhibitory effect in prostate cancer and thyroid cancer." (PMID 35942407, 2022). "Disruption of the KIBRA-Willin/FRMD6 interaction and Hippo signaling activation occurs in pathological conditions such as prostate cancer." (PMID 34831245, 2021). "Here, we found that HNRNPA2B1 and FRMD6 were negatively correlated in prostate cancer." (PMID 37215455, 2023). "In another study, researchers constructed a miRNA-mRNA regulatory network containing miR-106b-5p to identify genes such as TMEM100, FRMD6, NBL1, and STARD4 for the diagnosis and prognosis of prostate cancer patients." (PMID 38818039, 2024).
asthma (6 papers, 2012 to 2025). "FRMD6 has been linked to various complex diseases, such as asthma, Alzheimer’s disease, and lung cancer." (PMID 29236770, 2017). "FRMD6 has been linked to various complex diseases such as asthma, Alzheimer’s disease, and lung cancer, where it is thought to have tumor suppressor properties." (PMID 27454520, 2016). "Among the newly identified genes FRMD6 showed the strongest association with asthma, and we confirmed the possible role of this gene in the disease in an animal model and in human asthmatics." (PMID 22432035, 2012). "Association between a SNP in FRMD6 and asthma risk was identified with both the frequentist and BN-BMLA methods." (PMID 22432035, 2012). "With frequentist methods one SNP (rs3751464 in the FRMD6 gene) provided evidence for an association with asthma (OR = 1.43(1.2–1.8); p = 3×10−4)." (PMID 22432035, 2012). "The permutation based association test of Haploview indicated two haplotypes consisting of two SNPs (rs3751464 and rs17666653) in the FRMD6 gene for association with asthma." (PMID 22432035, 2012). "In that study the frequentist-based method identified two genes for asthma susceptibility (FRMD6 and PTGDR), while the BN-BMLA identified 3 additional genes." (PMID 23021489, 2012). "When allele frequencies were considered, one SNP (rs3751464) in the FRMD6 gene provided an evidence for an association with asthma (OR = 1.43 (1.18–1.75); p = 3×10−4)." (PMID 22432035, 2012). "The possible role of the FRMD6 gene in asthma was also confirmed in an animal model and human asthmatics." (PMID 22432035, 2012). "We compared the gene expression levels of genes found to be relevant in asthma in the SNP analysis in sputum samples of 12 asthmatics and 9 controls using TaqMan Gene Expression Assays (FRMD6, PTGDR, PTGER2, MS4A2, AHNAK, PRPF19, TXNDC16)." (PMID 22432035, 2012). "FRMD6 was reported to be a key upstream component of the Hippo signaling pathway, and Hippo signaling pathway is considered a key carcinogenic pathway for multiple tumors or asthma treatment." (PMID 33413358, 2021). "The most remarkable result of the study is the role of FRMD6 in asthma." (PMID 22432035, 2012). "In a partial genome screening of asthma we identified FRMD6 as a novel asthma gene." (PMID 22432035, 2012). "However, in all mice with OVA-induced experimental asthma the expression level of FRMD6 was consequently lower (in average with 1.52 fold)." (PMID 22432035, 2012). "The FERM domain containing 6 (FRMD6)/Hippo/YAP1 pathway may be involved in asthma pathogenesis." (PMID 40066231, 2025). "Altogether 5 SNPs in 4 genes were found relevant in connection with asthma phenotype: PRPF19 on chromosome 11, and FRMD6, PTGER2 and PTGDR on chromosome 14." (PMID 22432035, 2012). "In the BN-BMLA analysis altogether 5 SNPs in 4 genes were found relevant in connection with asthma phenotype: PRPF19 on chromosome 11, and FRMD6, PTGER2 and PTGDR on chromosome 14." (PMID 22432035, 2012).
Alzheimer disease (5 papers, 2016 to 2021). A progressive, neurodegenerative disease characterized by loss of function and death of nerve cells in several areas of the brain leading to loss of cognitive function such as memory and language. "In clinical studies, the FRMD6 gene is correlated with high significance to Alzheimer’s disease and cognitive impairment implicating a wider role of this protein in the nervous system." (PMID 32200438, 2020).
cervical cancer (5 papers, 2021 to 2024). A primary or metastatic malignant neoplasm involving the cervix. "Linc00887 inhibits the development of cervical cancer via activating the FRMD6-Hippo signal pathway and competitively binds miR-454-3p in cervical cancer." (PMID 36943627, 2023). "In conclusion, these findings indicated that Linc00887 sponging miR-454-3p inhibited the progression of cervical cancer through activating FRMD6-Hippo axis signaling pathway." (PMID 33413358, 2021). "In order to further understand the mechanism of linc00887 regulating the progression of cervical cancer, we detected effect of linc00887 on the expression of key proteins in FRMD6-Hippo signaling pathway." (PMID 33413358, 2021). "In all, our research revealed that linc00887 inhibited cervical cancer cell proliferation and invasion by adsorbing miR-454-3p and upregulating FRMD6 expression." (PMID 33413358, 2021). "Some studies have shown that FRMD6 inhibited the proliferation of human glioma cells, which is consistent with our tend in cervical cancer." (PMID 33413358, 2021). "In cervical cancer cells, microRNA miR-454-3p inhibits Willin/FRMD6 protein expression by binding to Willin/FRMD6 mRNA." (PMID 34831245, 2021). "MiR-454-3p targeted and suppressed the expression of FRMD6, and linc00887 suppressed tumorigenesis of cervical cancer through activating the FRMD6-Hippo signaling pathway." (PMID 33413358, 2021). "Next, we examined the FRMD6 mRNA level in cervical cancer cells, and we found that FRMD6 mRNA was downregulated in HeLa, C33A, Caski, ME180, Siha cells, compared with Ect1/E6E7 cells." (PMID 33413358, 2021). "Linc00887, sponging miR-454-3p, inhibited the progression of cervical cancer by activating the FRMD6-Hippo signaling pathway." (PMID 33413358, 2021). "In addition, LINC00887, which sponges miR-454-3p, inhibited the cervical cancer progression by activating the FRMD6-Hippo signaling pathway." (PMID 38338866, 2024).
lung carcinoma (5 papers, 2016 to 2024). "Here, FRMD6 is a poor independent prognostic factor for lung cancer, in favor of the protumor role in lung cancer." (PMID 37280069, 2023). "Nevertheless, FRMD6 expression also contributes to cancer progression by activating the mTOR signaling pathway, similar to what occurs in lung cancer." (PMID 38093305, 2023). "Surprisingly, FRMD6 bound and activated mTOR in lung cancer, suggesting its tumor promoting role." (PMID 38926528, 2024).
glioblastoma (4 papers, 2016 to 2024). The most malignant astrocytic tumor (WHO grade IV). "A further study confirmed that FRMD6 is downregulated in human glioblastoma cells and tissues and exerts its anti-glioblastoma effect largely through the negative regulation of MET RTK activity." (PMID 31221203, 2019). "In the nuclei of glioblastoma cells, FRMD6 colocalizes with c-Met, a growth factor receptor tyrosine kinase, suggesting that FRMD6 may regulate c-Met functions such as calcium signaling in the nucleus." (PMID 38296350, 2024). "Little is known about how FRMD6 functions and the potential role of FRMD in gliomagenesis and glioblastoma (GBM) progression." (PMID 27661120, 2016).
colorectal cancer (3 papers, 2016 to 2023). A primary or metastatic malignant neoplasm that affects the colon or rectum. "In the case of CC, FRMD6 is more strongly expressed in the serrated-type of colorectal cancer corresponding to colon cancer subtype 3 (CCS3)." (PMID 38093305, 2023). "Upregulation of FRMD6 has been suggested as a prognostic marker in colorectal cancer." (PMID 29236770, 2017). "It is worth noting that there have been no studies of epigenetic alterations of the FRMD6 and ZEB1 genes, which encode the proteins included in the panel, that are differentially expressed in colorectal cancer, as is demonstrated in Human Protein Atlas database." (PMID 38093305, 2023).
glioma (3 papers, 2016 to 2023). A benign or malignant brain and spinal cord tumor that arises from glial cells (astrocytes, oligodendrocytes, ependymal cells). "In addition, 8% (4/50) of glioma cell lines have FRMD6 deletion, which is consistent with the potential tumor suppressor function of FRMD6 in GBM." (PMID 27661120, 2016).
colon cancer (2 papers, 2013 to 2023). "In this study, we found that AMOLT1 and FRMD6 are co-overexpressed in TAZ-AXL-CTGF positive tumors, suggesting that AMOLT1 and FRMD6 may form a negative regulatory loop with TAZ activation, which requires further investigation in vitro in colon cancer cell line models." (PMID 23372686, 2013).
gastric cancer (2 papers, 2020 to 2023). A primary or metastatic malignant neoplasm involving the stomach. "FRMD6 was also reported to be upregulated in the poor survival CRC group by unknown causes and is also one of the panel of five key biomarkers of poor prognosis expressed in gastric cancer." (PMID 38093305, 2023). "-Analysis Type: Gastric Cancer vs. Normal Analysis-COL8A1; Analysis Type: Gastric Cancer vs. Normal Analysis-FRMD6; Analysis Type: Gastric Cancer vs. Normal Analysis-TIMP2; Analysis Type: Gastric Cancer vs. Normal Analysis-CNRIP1; Analysis Type: Gastric Cancer vs. Normal Analysis-GPR124." (PMID 32095347, 2020).
hippocampal atrophy (2 papers, 2021 to 2022). "Several GWAS and imaging studies have highlighted single nucleotide polymorphisms within the promoter and intron regions of the Willin/FRMD6 gene that are associated with AD risk and hippocampal atrophy." (PMID 34831245, 2021). "GWAS studies and AD neuroimaging studies have identified several variants within the gene for 4.1-ezrin-radixin-moesin (FERM) domain-containing protein 6 (FRMD6), also known as Willin, that are associated with AD risk and hippocampal atrophy." (PMID 36231104, 2022).
thyroid cancer (2 papers, 2022 to 2023). "A recent study demostrated that FRMD6 had a tumor suppressor role by suppressing the activation of carcinogenic YAP1 in thyroid cancer." (PMID 37215455, 2023).
aortic aneurysm (1 paper, 2021). A ruptured aneurysm located in the wall of the proximal portion of the descending aorta proceeding from the arch of the aorta. "The biological relevance of FRMD6, GNG2 and MBP with respect to the development of aortic aneurysms is unclear at this time." (PMID 34469433, 2021).
Charcot-Marie-Tooth disease type 2A (1 paper, 2022). "Mutations in MFN2 are associated with peripheral nerve degeneration in Charcot-Marie-Tooth disease type 2A, while Willin/FRMD6 is involved in peripheral nerve repair." (PMID 36231104, 2022).
hypertrophic cardiomyopathy (1 paper, 2020). A condition in which the myocardium is hypertrophied without an obvious cause. "GC samples in the FRMD6 and TIMP2 high expression group were significantly enriched for hypertrophic cardiomyopathy (HCM)." (PMID 32095347, 2020).
idiopathic pulmonary fibrosis (1 paper, 2024). Idiopathic pulmonary fibrosis (IPF) is a nonneoplastic pulmonary disease that is characterized by the formation of scar tissue within the lungs in the absence of any known cause. "Similarly, in TGF-β-enriched environments, such as fibroblastic foci (FF) from patients with idiopathic pulmonary fibrosis, FRMD6 co-localized with p16 in FF lining cells, while it was rarely detected in α-SMA-positive myofibroblasts that are abundant in FF." (PMID 38926528, 2024).
metastatic tumors (1 paper, 2023). "The results of transwell assays also demonstrated that the forced expression of FRMD6 clearly impaired the mobility of PCa cells, which was consistent with lower levels of FRMD6 in metastatic tumors." (PMID 37215455, 2023).
neoplasms of the brain (1 paper, 2022). "Although there is little research on FRMD3 in neoplasms of the brain, FRMD6 inhibits activation of tyrosine kinase receptors to overcome tumor growth and disease progression in GBM." (PMID 35887658, 2022).
squamous cell carcinomas of (1 paper, 2021). "Nuclear localization of Willin/FRMD6 is observed in squamous cell carcinomas of the head, neck, and upper aerodigestive tract." (PMID 34831245, 2021).
cancer (14 papers, 2010 to 2024). A tumor composed of atypical neoplastic, often pleomorphic cells that invade other tissues. "As a result, seven genes (FGF10, SERINE2, LSAMP, STXBP5, PDE5A, GLI2, FRMD6) were screened to develop the cancer associated fibroblasts (CAFs)-related risk signature (CAFRS)." (PMID 37280069, 2023). "Consistent with this role, FRMD6 exerts a tumor suppressive effect on most human cancers, including prostate cancer." (PMID 38926528, 2024). "FRMD6 was previously validated as a key upstream regulator of the Hippo signaling pathway that exerted an anti-tumor effect in several human cancers." (PMID 37215455, 2023). "The protumor role or anti-tumor role of FRMD6 varies among different cancer types." (PMID 37280069, 2023). "The FRMD6 gene is also altered in cancer but the causes of its aberrant expression have not been studied." (PMID 38093305, 2023). "Moreover, by recruiting the microprocessor protein DGCR8, HNRNPA2B1 positively modulated the processing of pri-miR-93 via an m6A-depenent way and subsequently inhibiting its target gene FRMD6, a cancer suppressor gene." (PMID 37215455, 2023). "FRMD6 has been identified as an upstream regulator of the Hippo signaling cascade, which regulates cell contact inhibition, apoptosis and proliferation, which themselves are known to be deregulated in CC and other cancers." (PMID 38093305, 2023). "Importantly, patients with high FRMD6 expressing cancers had a significantly higher chance to develop recurrences." (PMID 33673003, 2021). "Therefore, in advanced cancers, the loss of RASSF1A and the upregulation of FRMD6 might act synergistically to create a complex tumor microenvironment that facilitates tumor progression." (PMID 38926528, 2024). "Furthermore, it is interesting to note that upregulation of genes, such as ANKRD22, FRMD6, and KIR3DL2, and down-regulation of genes, such as TIMP3, SAP25, NAPSA, and TIMP are associated with a worse prognosis in cancer, are also associated with a worse prognosis in AdHF." (PMID 29236770, 2017). "Less information are available for six of the genes in the panel in relation to cancer namely the ITPRIP, FRMD6, CPXCR1, SLC38A9, MRPL52 and GFRA4." (PMID 27609023, 2016). "There is no agreement about what suppressor or oncogenic role FRMD6 alteration might play in cancer." (PMID 38093305, 2023).